VEGFA (vascular endothelial growth factor A)
Diseases named in the same sentence as VEGFA in open-access papers (continued):
Sharing a sentence is not in itself a finding about the gene and the disease.
glioma (continued). "While the mechanism by which XBP1, VEGFA and immune cells function remains unclear, XBP1 may present a new target for use in combination with VEGFA to treat glioma." (PMID 40621799, 2025). "P2X7R-mediated VEGFB secretion might also contribute to glioma angiogenesis by boosting VEGFA activity." (PMID 41034696, 2025). "These macrophages, in turn, secrete VEGFA to stimulate angiogenesis and support glioma growth." (PMID 39206155, 2024). "For example, miR-302e affects VEGFA expression to inhibit glioma progression." (PMID 38955795, 2024). "The expression level of γH2ax was upregulated and that of VEGFA was downregulated in glioma." (PMID 38750472, 2024). "EVs from glioma CSCs containing vascular endothelial growth factor A (VEGF-A) significantly boost angiogenesis and increase vascular permeability in brain endothelial cells, indicating significant contribution of CSC-derived EVs to the tumor’s vascular development." (PMID 38962016, 2024). "Finally, we confirmed that there are positive correlations among FBXO22, HIF-1α, and VEGFA expression in glioma patients." (PMID 38519492, 2024). "In accordance with our study, Burcu also found that VEGFA and CXCL8 were significantly overexpressed in patients with glioma, and that both VEGFA and CXCL8 could promote angiogenesis and accelerate the progression of LGG to GBM." (PMID 39488622, 2024). "Additionally, the Gal-9/Tim3 interaction promotes the polarization of M2 TAMs, which promotes glioma angiogenesis through VEGFA secretion." (PMID 37759870, 2023). "Additionally, we found that L1 overexpression resulted in upregulation of several VM formation‐related factors, including CD31, CD34, VEGFA, vimentin, and N‐cadherin, whereas it downregulated E‐cadherin expression in glioma cells." (PMID 36708044, 2023). "In a previous study, we found that miRNA-383-5p may be an important factor in regulating the malignant biological behavior of glioma using a bioinformatics tool, and its downstream target was predicted to be vascular endothelial growth factor A (VEGFA)." (PMID 37592783, 2023). "Interestingly, we observed a significantly lower expression of genes such as PDGFA, FGFR1, DLL4, and VEGFA in glioma patients with a higher TMIGD2 profile." (PMID 37261362, 2023). "All data suggest that circITGA7 promotes glioma tumorigenesis by the miR-34a-5p-VEGFA axis." (PMID 37234708, 2023). "There is also evidence for this variant influencing VEGF-A levels in non-CVDs such as glioma and diabetic retinopathy.The variant rs3025039, located within exon 8 of VEGFA, has similar effects." (PMID 37288254, 2023). "VEGFA, a crucial molecular of tumor angiogenesis, plays a critical role in endothelial cell proliferation, migration, and tube formation, and has also been reported to promote cell cycle, proliferation, and metastasis in glioma as an oncogene." (PMID 36479622, 2023). "In addition, the results showed that Survivin, VEGFA, and c-Myc levels were lower in U251, RG-2, LN-428, and U87-MG cells than in normal glioma cells." (PMID 37057281, 2023). "In general, circ-RPL15 might promote glioma progression by suppressing miR-146b-3 and thus upregulating VEGFA activity." (PMID 37234708, 2023). "Collectively, the data indicate that SPRY4‐IT1 could enhance VEGFA expression via the miR‐101‐3p/EZH2 signaling axis in glioma cells." (PMID 36479622, 2023). "The first reports of vascular endothelial growth factor A (VEGFA) expression by glial cells date back to the early 90s in human gliomas in the process of retinal angiogenesis in rats or cats or in vitro in rat astrocyte cultures subjected to hypoxic conditions." (PMID 37936690, 2023). "In summary, the present studies indicate that lncRNA SPRY4‐IT1 regulates VEGFA expression to facilitate cell proliferation and angiogenesis of glioma via the miR‐101‐3p/EZH2 axis, and our findings provide mechanistic insights into potential strategies for anti‐angiogenic therapy in glioma." (PMID 36479622, 2023).
glioma (continued). "The expression of miRNA-383-5p has been found to be decreased in glioma and VEGFA may be a downstream target." (PMID 37592783, 2023). "TAM-secreted VEGFA stimulates angiogenesis and supports glioma growth." (PMID 38250074, 2023). "We observed high CD31, EGFR, and VEGFA expression predicted poor prognosis in glioma patients." (PMID 37534312, 2023). "Additionally, HOXC10 up-regulated the expression of VEGFA, enhancing the capacity of glioma angiogenesis, which made it a potential therapeutic target for antiangiogenic therapy." (PMID 37334354, 2023). "The upregulation of VEGFA is related to the increased apoptosis of glioma cells." (PMID 37592783, 2023). "SPARC is highly expressed in GBM, where it promotes the migratory and invasive behavior of glioma cells; moreover, by suppressing tumor vascularity, through the abrogation of VEGFA expression and inhibition of VEGFR2 phosphorylation, it inhibited glioma growth and VEGF-induced DNA synthesis." (PMID 35054871, 2022). "Interestingly, PRMT5 was required for the overexpression of VEGFA mediated by HOXC10 representing a potential target for anti-VEGF therapy in glioma therapeutics." (PMID 33440687, 2021). "Given the high abundance and strong expression of Vegfa/VEGFA in TAMs, interference with VEGF signaling could furthermore lead to enhanced antitumor responses, as shown in a triple treatment approach of murine glioma." (PMID 34539650, 2021). "As a result, we showed circITGA7 promoted VEGFA expression via sponging miR-34a-5p in glioma." (PMID 33962397, 2021). "Thus, VEGFA can serve as not only a prognostic biomarker for predicting gliomas' prognosis but also a potential immunotherapeutic target in the near future." (PMID 34497663, 2021). "Collectively, m6A RNA methylation regulators KIAA1429, METTL16, METTL3, IGF2BP2, and YTHDF, and targets NASP, TIMP1, U2AF2, COL18A1, and VEGFA could serve as oncogenes in glioma, while PHLPP2 is a tumor suppressor." (PMID 34589481, 2021). "LRIG2 was proven as miR-503 target by luciferase assay, knockdown of LRIG2 reduced VEGFA expression level along with the condition of miR-503 inhibitor, therefore, miR-503 regulated angiogenesis in glioma by reducing LRIG2 expression followed by downregulation of VEGFA expression." (PMID 33762949, 2021). "PRMT5 interacts directly with HOXC10, promoting the enrichment of H3R2me1 and H3R2me2s on the VEGFA promoter, and then recruiting WDR5 for subsequent methylation of H3K4 on the VEGFA promoter, which eventually leads to the transcription of VEGFA and promotes angiogenesis in glioma." (PMID 34513846, 2021). "Nevertheless, suppressed miR-34a-5p induced glioma cell growth, migration and invasion, whereas those effects could be reversed once down-regulation of VEGFA in glioma cells." (PMID 33962397, 2021). "In our present study, four progression-related DE IRG (including VEGFA, SOCS3, SPP1, and TGFB2 genes)constituting a signature can perform risk stratification for glioma patients and disclosed that patients with high risk seemed to have an approximate 14.3%-29.8% 5-year survival rate." (PMID 34497663, 2021). "In this study, we found that B7H3 was positively correlated with VEGFA in gliomas." (PMID 34079802, 2021). "Our study established and validated a seven-gene signature comprising METTL3, COL18A1, NASP, PHLPP2, TIMP1, U2AF2, and VEGFA, with a good capability for predicting glioma survival, which may guide therapeutic customization and clinical decision-making." (PMID 34589481, 2021). "Notably, the expression of B7H3 and VEGFA were both further reduced in 2-HGhigh gliomas compared to that in 2-HGlow gliomas." (PMID 34079802, 2021). "We also proved that RPL34-AS1 mediates angiogenesis in glioma by regulating VEGFA." (PMID 34539892, 2021).
glioma (continued). "Also, HOTAIR expression correlates with angiogenesis via modulation of VEGFA expression, one of the most important factors in tumor angiogenesis, and transmission of this factor to endothelial cells through glioma cell-derived extracellular vesicles." (PMID 33980320, 2021). "It is well known that VEGFA is one of the most important factors in glioma angiogenesis." (PMID 34539892, 2021). "H19 silencing reversed glioma cell growth and metastasis by regulating the miR-342-mediated Wnt5a/β-Catenin signaling pathway with decreased levels of vascular endothelial growth factor A (VEGFA), MMP9, Wnt5a, and β-catenin." (PMID 34977037, 2021). "Moreover, VEGFA secretion values in both glioma groups were higher than in healthy donors (P < 0.01) and correlated with the tumor grade." (PMID 32564774, 2020). "Together, these results demonstrate that glioma patients could be divided according to VEGFA expression and secretion levels." (PMID 32564774, 2020). "In summary, we discovered the molecular regulatory network in which SRSF10 facilitated circ-ATXN1 biogenesis and subsequently increased its binding with miR-526b-3p to inhibit the negative regulatory effect of miR-526b-3p on MMP2 and VEGFA in regulating glioma angiogenesis." (PMID 32600379, 2020). "Additionally, we further verified the biological function of exocrine VEGFA in overexpressed NKILA glioma cells with Bevacizumab, which can specifically bind to VEGFA and block its biological function." (PMID 32382013, 2020). "Importantly, glioma stem cells also produce VEGFA protein which is carried in extracellular vesicles and induce the formation of blood vessels by targeting brain endothelial cells." (PMID 33036421, 2020). "In addition, we found several hub genes with worse OS and higher expression level in glioma patients, including VEGFA, NDC80, TIMP1, SAA1, CENPA, CENPF, and NCAPG and we firstly found relationship of SAA1, TIMP1, and molecular pathology in GBM." (PMID 30867991, 2019). "Enhanced glioma tumorigenicity upon CBS loss was associated with upregulation of HIF-2α protein level and HIF-2α-dependent transcriptional activation of angiopoietin like 4 (ANGPTL4) and vascular endothelial growth factor A (VEGFA)." (PMID 30050925, 2018). "A study in glioma showed that the inhibition of fatty acid synthase suppresses neovascularization by regulating the expression of vascular endothelial growth factor A (VEGF-A)." (PMID 29361784, 2018). "Finally, numerous studies have demonstrated that VEGFA is also a possible mediator of tumor-induced angiogenesis in glioma." (PMID 29137376, 2017). "No individual eligible studies focused on VEGFA polymorphisms rs1413711 and rs3025035 revealed any statistically significant positive correlations associated with glioma risk." (PMID 29137376, 2017). "Based on these roles in glioma development, over 30 SNPs in the VEGFA gene have been described." (PMID 29137376, 2017). "This differential activation status of VEGFA between GL261 and LLC tumors correlates with the level of immune cell marker gene infiltration in each tumor model and is consistent with the requirement for VEGFA/VEGFR2 signaling for CPA to activate immune cell recruitment in responding gliomas." (PMID 27515027, 2016). "Our initial hypothesis was that dexamethasone may affect glioma growth species-specific and regulate key factors of edema formation, namely xCT and VEGFA expression." (PMID 24714627, 2014). "Furthermore, DEXA induces xCT and VEGFA expression in murine and rodent gliomas as early responses of cell stress." (PMID 24714627, 2014). "In support of this are former reports, demonstrating DEXA as a VEGFA suppressor in gliomas." (PMID 24714627, 2014). "Thus suppression of VEGFA is likely only one of several probable mechanisms underlying EFEMP1 suppression of glioma growth and EFEMP1 exhibits some VEGF-independent anti-tumor effects." (PMID 21955618, 2011).
glioma (continued). "We detected genes upregulated in PBT030 cells, such as SOX2, MYCN, NOS2, RUNX2, and VEGFA, while PBT147 cells upregulated level of PTEN, STAT6, CA9 and TLR2, demonstrating differences among PBT cell lines, which can be explained by various driving mutations and heterogeneity in glioma lines." (PMID 38449858, 2024). "Therefore, it would be interesting to investigate whether IDO1 could deplete Trp, thereby activating the GCN2 pathway, which can be detected using C/EBP homologous protein (CHOP) as a marker, and upregulating VEGFA expression in glioma." (PMID 39065567, 2024). "Therefore, we hypothesized that low levels of miRNA-383-5p could promote the malignant biological behavior of glioma by regulating the expression of VEGFA, and overexpression of VEGFA could reverse the effect, thus potentially identifying a therapeutic target." (PMID 37592783, 2023). "Moreover, HOXC10 induces angiogenesis by upregulating the expression of VEGFA, and may be a potential antiangiogenic target for glioma." (PMID 38154103, 2023). "Furthermore, immunoblotting analysis was performed to detect whether the expression of EZH2 and VEGFA are regulated by SPRY4‐IT1 in glioma cells." (PMID 36479622, 2023). "Therefore, targeting SPRY4‐IT1/miR‐101‐3p/EZH2/VEGFA axis may improve the outcomes of patients with glioma." (PMID 36479622, 2023). "In glioma, recent studies have reported that immunotherapy such as anti-PD-1 and anti-VEGFA could predominantly prolong the survival of some glioma patients, but the response population was not stable, only a subset of patients could benefit from immunotherapy." (PMID 34307451, 2021). "However, further investigation is needed to explore whether and how B7H3 regulates VEGFA in gliomas." (PMID 34079802, 2021). "Moreover, VEGFA expression was regulated by circITGA7 and miR-34a-5p together in glioma." (PMID 33962397, 2021). "Functional enrichment analysis demonstrated that BrM‐ and glioma‐upregulated proteins were significantly enriched in pathways related to extracellular matrix (ECM) organization, neutrophil degranulation, and VEGFA‐VEGFR2 signaling." (PMID 39716938, 2025). "Our results showed that the expression levels of FBXO22, HIF-1α, and VEGFA in high-grade gliomas were much higher than those in low-grade gliomas, while the expression level of VHL in high-grade gliomas was much lower than that in low-grade gliomas." (PMID 38519492, 2024). "Bioinformatic analyses showed that the expressions of IDO1 and angiogenesis markers VEGFA and CD34 were positively correlated and increased with pathological grade in glioma." (PMID 39065567, 2024). "Understanding the multiple functions of VEGFA and its regulation by lncRNA INC0116 has been shown in glioma tumorigenesis." (PMID 39682093, 2024). "The expression of FBXO22, VHL, HIF-1α, and VEGFA was detected by IHC staining using anti-FBXO22, VHL, HIF-1α, and VEGFA antibodies in the tissue sections of glioma patients." (PMID 38519492, 2024). "In this study, we investigate the mechanism by which IDO1 induces angiogenesis in glioma and aim to provide new evidence supporting dual IDO1 and VEGFA blockade as a viable anti-tumor therapeutic strategy." (PMID 39065567, 2024). "A significant increase in serum VEGFA concentration and tumor CD34 expression was observed in IDO1-overexpressing GL261 subcutaneous glioma-bearing mice." (PMID 39065567, 2024). "Consistent with what we observed in glioma cells, IDO1 overexpression also upregulates VEGFA through GCN2 activation in mice." (PMID 39065567, 2024). "In glioma tissue sections, it was observed that the expression levels of IDO1, VEGFA, and CD34 were positively correlated with the pathological grades, with expression levels in grade III/IV glioma patients significantly higher than in patients of lower grade." (PMID 39065567, 2024).
glioma (continued). "SRSF10 upregulates the production of a circular RNA (CIRC-ATXN1) that plays a role in glioma angiogenesis by sequestrating mir-526b-3p, which normally inhibits the expression of pro-angiogenic MMP2 and VEGFA." (PMID 36611187, 2023). "Collectively, these data indicated that SPRY4‐IT1 promoted glioma cell proliferation and angiogenesis via the miR‐101‐3p/EZH2 axis by mediating VEGFA downregulation." (PMID 36479622, 2023). "Rescue experiments further confirmed that SPRY4‐IT1 promoted glioma cell proliferation and angiogenesis via the miR‐101‐3p/EZH2/VEGFA signaling axis." (PMID 36479622, 2023). "Mechanistically, we then assessed the protein levels of VEGFA, MMP2, and MMP9 in glioma cells after treatment with the miR‐143‐3p inhibitor and/or MEK‐2206." (PMID 36708044, 2023). "Expression profiling of the peritumoral brain around IDHmut gliomas also showed upregulation of SLC12A5, THBS1, VEGFA, FOSL2, and SYNPO, as has been previously reported in epileptic brain tissue." (PMID 37104042, 2023). "TGFB1, VEGFA, ARG1, and IL10 are secreted immunosuppressive factors in glioma, while CD70 is a glioma cell-surface immunosuppressive factor." (PMID 37891828, 2023). "We further elucidated that SPRY4‐IT1 promotes glioma cell proliferation and angiogenesis in vitro and in vivo, and activates the miR‐101‐3p/EZH2/VEGFA pathway." (PMID 36479622, 2023). "Neutrophils promote glioma growth via induction of S100A4 expression in glioma cells, and S100A4 deletion increased the efficacy of anti-VEGFA therapy in tumor-bearing mice." (PMID 36594465, 2023). "Based on univariate and multivariate cox regression analysis, we identified five genes, FABP5, VEGFA, SAA1, ADM, and PRLHR, for prognosis prediction in patients with glioma." (PMID 35800054, 2022). "A recent comparative RNA-seq analysis identified that many genes are commonly upregulated in both gliomas (eg., IDH wild-type) and BrMs, including the angiogenic factor VEGFA, growth factors PDGFA, TGFB1, SPP1, and the protease inhibitor TIMP-116." (PMID 36216799, 2022). "On the other hand, miR-153 declines the expression of angiogenesis promoting factors such as VEGFA and cdc42 by binding to 3 ́UTR of their mRNAs in glioma." (PMID 36158686, 2022). "TGFB1, VEGFA, ARG1, FGL2 and IL10 are secreted immunosuppressive factors in glioma, while CD95L and CD70 are glioma cell‐surface immunosuppressive factors." (PMID 33611848, 2021). "In glioblastoma, CSCs generate higher levels of the chemoattractants C-C motif chemokine ligand 2 (CCL2), CCL5, vascular endothelial growth factor-A (VEGF-A), and neurotensin than the bulk of the glioma." (PMID 34235155, 2021). "Analysis of the Chinese Glioma Genome Atlas Network (CGGA) dataset showed that higher SOCS3, VEGFA, and TEK expression levels are observed in GBM cases with wildtype (WT) IDHs." (PMID 33804433, 2021). "MDSCs release vascular endothelial growth factor A (VEGFA) and matrix metalloproteinases (MMP2 and MMP-9) to promote glioma growth." (PMID 33452462, 2021). "We also performed ELISA detection and found that BATF2 upregulation significantly decreased VEGFA, MMP2, and MMP-9 levels in glioma tissues (VEGFA: p < 0.001; MMP2: p < 0.01; MMP-9: p < 0.01) and exhibited decreased MMP-9 staining in U251-BATF2 tumour." (PMID 33452462, 2021). "CircSCAF11 activates the VEGFA transcription via the miR-421/SP1/VEGFA axis, which stimulates angiogenesis and tumourigenesis of glioma." (PMID 31973726, 2020). "In glioma cells, PAX6 suppressed the expression of vascular endothelial growth factor A and the angiogenesis of glioma cells." (PMID 33182335, 2020). "Our study showed that celastrol obviously reduced the numbers of VM channels and EVs and the expression of CD31, VEGFR2, Ang2, VEGFA, EphA2, and VE-cadherin in glioma xenograft tissues, indicating that celastrol might suppress tumor growth by inhibiting angiogenesis and VM formation in glioma." (PMID 32116702, 2020).